ITGB2 (integrin subunit beta 2)
Diseases named in the same sentence as ITGB2 in open-access papers (continued):
Sharing a sentence is not in itself a finding about the gene and the disease.
tumor (continued). "In conclusion, ITGB2 is a tumour‐promoting gene in CRC, and silencing ITGB2 may be a novel therapeutic strategy for CAC." (PMID 39088353, 2024). "Other ligand-receptor pairs revealed by this analysis included TNF-TNFRSF1A sent by medium-SORL1 expressing GAMs, TNFSF12-TNFRSF12A (high-SORL1 GAMs to tumor cells), PDGFB-PDGFRA (medium- and high-SORL1 GAMs to several populations), and THY1-(ITGAM + ITGB2) received by high-SORL1 GAMs (Fig. EV2B)." (PMID 38499808, 2024). "Overexpression of ALYREF and YBX1 was accompanied by the upregulation of immune checkpoint inhibitors (such as CD276 and PDCD1) and downregulation of immune checkpoint stimulants (such as CX3L1, ITGB2, CD40LG and SELP), which promoted evasion of immune surveillance by these tumor cells." (PMID 38238581, 2024). "However, the expressions of IGKC, IGLC1, ITGB2, CTSS, HLA‐DPB1, and RSAD2 were elevated in tumor tissue and they served as protective factors." (PMID 37543714, 2023). "We observed that MFAP5 + fibroblasts were the main senders that could release complement C3 to interact with the receptors ITGAM/ITGB2, ITGAX/ITGB2, and C3AR1 of C1QC + macrophages in tumor tissues, thus activating the complement system." (PMID 37344903, 2023). "Regarding the non-tumor disorders, studies suggested that the upregulated mRNA expression level of ITGB2 in PBMCs (peripheral blood mononuclear cells) did not associate with disease severity of SSc patients, nor did the status in premature infants with NEC." (PMID 36980477, 2023). "Finally, the TIMER (tumor immune estimation resource) database was employed to evaluate the interactions between ITGB2 and the immune infiltration in the TME (tumor microenvironment)." (PMID 36980477, 2023). "We observed an overexpression of neutrophil intracellular marker protein (MPO) and cell surface marker proteins (CEACAM8, ITGAM and ITGB2) in early stage GBC in comparison to GSD (non-tumor controls) suggesting neutrophil infiltration in tumor tissue." (PMID 36686780, 2022). "We observed that CCR5 (cor=-0.3, P=1.63e-07), FCER1G (cor=-0.269, P=2.97e-06) and ITGB2 (cor=-0.279, P=1.12e-06) were all significantly correlated with tumor purity in a negative manner." (PMID 33995630, 2021). "In addition, higher ITGB2 expression in CAFs was correlated with higher TNM stages and more Ki67+ tumor cells, indicating its ability to promote OSCC proliferation." (PMID 33204328, 2020). "In addition, IFC analysis of ITGB2 in the OSCC tumor microenvironment also showed that ITGB2 expression was positively correlated with CAFs markers, α-SMA, further confirming ITGB2 expression in CAFs." (PMID 33204328, 2020). "Among receptors expressed on NK cells, inhibitory receptors (KIR2DL4; CD94) and activating receptors (ITGB2; KIR2DS5; NKG2C/E; NKp46) were identified which may work as sensors to discriminate normal cells and tumor cells." (PMID 25826780, 2015). "Compared to naïve HL-60 human promyelocytic leukemia cells, which cannot be engulfed by tumor cells, differentiated HL-60 (dHL-60) neutrophils, which can be engulfed by tumor cells, express several integrin family genes, such as ICAM-1, ITGAM, ITGB2, ITGAX, and ITGAV, at higher levels." (PMID 39941753, 2025). "We examined the expressions of ITGA6 and ITGB2 across these samples and found that ITGA6, but not ITGB2, was highly expressed in fibroblasts in OM compared to AT and PT, supporting that tumor-derived ITGA6-high exosomes are predominantly uptaken by fibroblasts in ovarian tissues." (PMID 40860157, 2025). "Moreover, Pearson correlation analysis revealed a negative correlation between tumor ITGB2 scores and survival time (R = ‐0.41, P = 0.0021)." (PMID 40071217, 2025). "ITGB2 (CD18) is a key subunit of the β2 integrin in tumor cells that can participate in cell adhesion matrix remodeling and signal transduction between tumor cells and the microenvironment, thus inducing infiltration, angiogenesis and specific immune responses in tumor cells." (PMID 38345576, 2024).
tumor (continued). "In fact, tumor cDC1s, cDC2s and TAMs from XBP1ΔDC mice display signs of RIDD at protein level, as surface expression of the integrin CD11c, an obligate dimeric partner of the RIDD substrate Itgb2 (coding the integrin CD18) is reduced in tumor cDC1s from XBP1ΔDC mice." (PMID 37346037, 2023). "Moreover, these genes may play important roles in promoting tumor angiogenesis (CXCL13, ZAP-70, and CCL19), tissue remodeling (ITGAM and ITGB2), and immunosuppression (CD4 and IL-10) in cancer cell lines or samples." (PMID 32509861, 2020). "ITGAL, GBP1, GBP2 and ITGB2 were all upregulated in TLS positive tumors compared to TLS negative, but no changes could be observed in Tumor versus Normal and TLS positive versus Normal." (PMID 30082828, 2018).
cancer (90 papers, 2007 to 2026). A tumor composed of atypical neoplastic, often pleomorphic cells that invade other tissues. "ITGB2 is overexpressed in several cancers, and its expression levels are associated with disease progression and poor prognosis." (PMID 40071217, 2025). "Nowadays, with the continuous deepening of research, ITGB2 has been found to be associated with some cancers." (PMID 39825491, 2025). "For example, one study demonstrated that ITGB2 promotes OSCC proliferation by enhancing glycolytic activity in cancer-associated fibroblasts (CAFs) through the PI3K/AKT/mTOR pathway." (PMID 41181127, 2025). "Given the crucial role of integrins in cancer progression, the upregulation of ITGB2 in TNBC tissues and serum EVs is likely associated with TNBC development." (PMID 40071217, 2025). "FAHD1+epi cells interact with cancer-associated fibroblasts through ITGB2-mediated interactions, facilitating the formation of a transforming growth factor-β/vascular endothelial growth factor-enriched niche that promotes immune evasion." (PMID 40814172, 2025). "Integrin beta 2 (ITGB2) plays a pivotal role in promoting OSCC proliferation in CAFs by enhancing the glycolytic activity of cancer-associated fibroblasts (CAFs) via the PAM pathway." (PMID 39595043, 2024). "ITGAL and ITGB2 are associated with carcinogenesis and immune regulation, and are considered prognostic biomarkers for various cancers." (PMID 39684926, 2024). "Related studies have shown that ITGB2 mediates mitochondrial glycolytic transformation in cancer-associated fibroblasts through the PI3K-AKT-mTOR pathway and participates in the occurrence, metastasis and invasion of oral squamous cancer cells." (PMID 38345576, 2024). "Though there are in-silico and in-vitro studies that associated the ITGB2 as one of the important genes in cancer, the exact mechanisms of how this gene promotes GBM remains elusive and worth to be investigated in the future." (PMID 34301218, 2021). "RT-PCR and western blot were used to compare ITGB2 expression in normal fibroblasts (NFs) and cancer associated fibroblasts (CAFs)." (PMID 33204328, 2020). "Importantly, genes associated with cancer progression (i.e., Itgb2, Itgb5, paxillin, fyn) displayed increased expression, whereas those thought to suppress progression (i.e., vinculin, gravin) exhibited decreased levels of expression compared to MOSE-E cells." (PMID 21390237, 2011). "This study investigates the role of cancer‐derived extracellular vesicle (EV) integrin beta‐2 (ITGB2) in TNBC progression." (PMID 40071217, 2025). "Specifically, we found that CTNNB1 mutated carcinomas showed significantly downregulated levels of ITGAL, ITGAM, and ITGB2, which are involved in leukocyte transendothelial migration." (PMID 41227323, 2025). "Zhang found that ITGB2 promoted glycolysis and lactic acid secretion through the PI3K-AKT-mTOR pathway in cancer-associated fibroblast cells and enhanced NADH-dependent OXPHOS function in mitochondria through lactic acid oxidation." (PMID 38345576, 2024). "Our study indicates that ITGB2 is significantly upregulated in several cancers, consistent with previous reports." (PMID 39088353, 2024). "The involvement of Itgb2 in promoting cancer cell proliferation in cancer by mediating the oxidation of NADH in the mitochondrial oxidative phosphorylation system has also been demonstrated in existing studies." (PMID 37063847, 2023). "ITGAM and ITGB2 are subunits of integrin, and these cell adhesion-related molecules are closely related to cancer cell invasion and metastasis." (PMID 36615183, 2023). "We decided to determine the effects of binase treatment and ITGB2-LOF on cancer hallmarks in SCLC cells." (PMID 37215577, 2023). "The immunohistochemistry assay showed that ITGB2 was expressed higher in normal tissues than in cancer tissues." (PMID 36362654, 2022).
cancer (continued). "ICAM-1 on target cells binds to its cognate receptor LFA-1 (ITGAL/ITGB2) on effector lymphocytes (e.g., CTLs and NK cells), strengthening the interaction between the cytotoxic killer cells and carcinoma target cells." (PMID 35572601, 2022). "The transcriptional co-activator Yes-associated protein (YAP) induced the expression of integrin subunit ITGB2, which increased cancer cell invasion." (PMID 33593435, 2021). "Consistently, RT-PCR confirmed that ITGB2 mediated lactate release altered some gene expression of mitochondrial complex I in nearby cancer cells." (PMID 33204328, 2020). "In our study, ITGB2 was also found to be overexpressed in cancer cells, proved by IHC and immunofluorescence analyses of ITGB2 in OSCC patients." (PMID 33204328, 2020). "ITGB2 expression in cancer cells promotes cell invasion through the endothelium in leukocyte-like manner." (PMID 32664456, 2020). "As to the cell cohesion molecules, only ITGB2 exhibited a relatively strong correlation with PD-1 in some types of cancer." (PMID 30607140, 2018). "Subsequently, we performed FACS detection of CAMs, and the results showed that cancer group cells had increased CD18 (ITGB2), CD106 (VCAM-1), and CD31 (PECAM-1), with decreased CD54 (ICAM-1)." (PMID 28350008, 2017). "To explore whether ITGB2 could affect the immunotherapy response outcome of cancer patients, we first analyzed the expression of immune checkpoints and TIDE score in ITGB2high and ITGB2low groups." (PMID 39960961, 2025). "ITGB2 has been reported to activate pro-survival signals in cancer cells." (PMID 40464949, 2025). "However, further experimental evidence is needed to prove the potential immune regulatory effects of ITGB2 in cancers." (PMID 38814534, 2024). "Moreover, pan‐cancer analysis using TCGA datasets revealed that ITGB2 was significantly upregulated in several cancers." (PMID 39088353, 2024). "Moreover, high expression of ITGB2 was also reported to be correlated with poor prognosis in some cancers." (PMID 38022584, 2023). "However, confirmation of the direct link between the hypoxic HDAC6-SMAD3-SARA pathway and the ITGB2/VIM effect on hypoxia-induced cancer cell invasion will require further investigation." (PMID 35681731, 2022). "Furthermore, gene expression of the integrins Itgal, Itgb2 and Itgax responsible for the regulation of development, immune response, cancer development, and homeostasis was upregulated." (PMID 34185104, 2021). "Although previous studies showed that integrin beta 2 (ITGB2) is important for host defense, its expression profile and role in tumors, especially in cancer associated fibroblasts (CAFs) are still unknown." (PMID 33204328, 2020). "Apart from cancer cells, here we showed that ITGB2 was also expressed in CAFs." (PMID 33204328, 2020). "Interestingly, our investigation is the first one that shows the strong correlation between cell adhesion molecule gene ITGB2 and PD-1 in some cancer types." (PMID 30607140, 2018). "Finally, we found that ITGB2 was correlated with IC50 of cancer drugs." (PMID 39960961, 2025). "Notably, ITGB2 has been implicated in cancer-associated fibroblast (CAF)-mediated glycolytic activation and pyruvate-lactate secretion, suggesting a feedforward loop where FAHD1+epi cells engage CAFs through ITGB2 to reinforce metabolic symbiosis." (PMID 40814172, 2025). "However, the biological mechanisms of the interactions between TNXB-SDC4, THY1-(ITGAX+ITGB2), ICAM1-(ITGAX+ITGB2), and C3-(ITGAX+ITGB2) ligand-receptor pairs in cancer remain unclear and warrant further investigation." (PMID 37954130, 2023). "Additionally, ITGB2 has the potential to be an indicator of pan-cancer immune infiltration." (PMID 36980477, 2023). "Notably, the pro-proliferative activity of ITGB2-expressing CAFs may also provide an advantage for cancer treatment as OSCC cells cultured in ITGB2-expressing CAFs medium render OSCC cells sensitive to metformin." (PMID 33204328, 2020).
cancer (continued). "In addition, ITGB2 might correlated with response to immunotherapy in cancer." (PMID 39960961, 2025). "Further analyses showed that these high HLA‐DR+ cancer cell tumors exhibited elevated levels of LAG3, TNFRSF9, CTLA4, PDCD1, TIGIT, ITGB2, and GZMB." (PMID 40464412, 2025). "Our results demonstrated the complementary expression of ITGB2 and ITGB6 in SCLC and LUAD suggesting their use as markers for these cancer subtypes and supporting the formation of different integrin heterodimer receptors in SCLC and LUAD." (PMID 37215577, 2023). "Altogether, these results support a role for ITGB2 and VIM in the SMAD3-dependent pro-invasive properties of cancer cells that are accentuated by hypoxic conditions." (PMID 35681731, 2022). "This study investigates the role of cancer‐derived extracellular vesicle (EV) integrin beta‐2 (ITGB2) in the progression of triple‐negative breast cancer (TNBC)." (PMID 40071217, 2025). "The ITGB2, CSF1, and CXCR2 genes are closely related to cancer." (PMID 39771147, 2024). "Platelet activation, focal adhesion, proteoglycans in cancer, axon guidance, phagosome, glutamatergic synapse and MAPK1, FRS2, FDGFRA, SHC1, ITGB2 and ITGA1 may be the core bio-pathway and genes involved in direct intervention, respectively." (PMID 28380454, 2017). "Similarly, vital immune checkpoint genes such as HAVR2, CD274, CTLA4, ITGB2, ICAM1, CCL5, CXCL10 all exhibited robust correlation with IFI30, and this immunotherapy might, in the future, establish a bond with IFI30, bringing new opportunities for cancer treatment." (PMID 39925804, 2025).
infection (86 papers, 2001 to 2026). The state of being infected such as from the introduction of a foreign agent such as serum, vaccine, antigenic substance or organism. "Human neutrophils harboring genetic mutations in ITGB2, the gene encoding CD18, are unable to exit circulation and migrate towards sites of infection." (PMID 39899622, 2025). "Human neutrophils harboring genetic mutations in ITGB2 are unable to exit circulation and migrate towards sites of infection." (PMID 39416161, 2024). "Furthermore, the heatmap of the DEG list highlighted the significant upregulation of multiple genes related to the complement system on D1 and D7 post-infection, including complement C3, C3ar1, Itgax, Itgb2, and C1ra." (PMID 40294039, 2025). "ITGB2 plays a role in leukocyte recruitment to sites of inflammation and infection." (PMID 41012626, 2025). "LAD-1 is an autosomal recessive disorder with defects in the gene encoding a critical leukocyte adhesion molecule (ITGB2 encoding CD18) required for neutrophils to adhere to ICAM molecules on endothelium to leave the bloodstream and move to sites of infections." (PMID 33717203, 2021). "Among the signals from LZ GC B cells to DCs, multiple MHC II protein complex subunits exhibited enhanced interaction with Cd4, while signals including Fcer2a-(Itgax+Itgb2) and Cd22-Ptprc were weakened by PCV2 infection." (PMID 41011514, 2025). "Relative gene expression of ITGB1, ITGB2 ITGB3 and CAV-1 in THP-1 or HUVEC were analysed by comparing treatment of 4h leptospires infection and non-infection." (PMID 36137081, 2022). "Genes that were down-regulated genes at 24h post infection included inflammatory and anti-pathogen genes (CSF1 and USP2) and the cell apoptosis and death genes (MICB, BUB1B, ITGB2, UBB and BIRC3)." (PMID 23527143, 2013). "The membrane glycoprotein LFA-1, an integrin which is composed of the integrin alpha L chain ITGAL (CD11) and the beta 2 chain ITGB2 (CD18) is expressed on T-cells, were it functions in recruitment of the cells to the site of infection and interacts with antigen-presenting cells." (PMID 29453458, 2018). "Interestingly, Il2rg and Itgb2 stand out as two robust reference genes for gene expression analysis in spleens of BALB/c mice, regardless of infection with an intracellular parasite whose target organ is spleen, among others." (PMID 27668434, 2016).
neurodegenerative disease (6 papers, 2015 to 2024). A disorder of the central nervous system characterized by gradual and progressive loss of neural tissue and neurologic function. "ITGB2 has been reported to have functional roles in neurodegenerative diseases, including PD." (PMID 39483867, 2024).
kidney disease (3 papers, 2024 to 2025). "They displayed CpG sites located near genes such as ZNF20 and ITGB2, which are known to be enriched for functional roles in kidney diseases." (PMID 38879526, 2024). "However, current research on the relationship between ITGB2, RAC2, and kidney disease remains inadequate." (PMID 40369957, 2025).
inflammation (2 papers, 2022 to 2023). Aberrant reaction of the microcirculation characterized by movement of fluid and leukocytes from the blood into extravascular tissues. "Although RA and OA have quite different causes, they share synovial inflammation, risk factors, and some disease-associated genes, including the integrin subunit β2 (ITGB2)/CD18 gene involved in extracellular matrix interactions and immune cell signaling." (PMID 37644537, 2023).
ITGB2 also shares sentences with these, for which no sentence is quoted: pancreatic cancer (36 papers); bacterial infections (9); pneumonia (9); endotoxemia (5); leukocytosis (5); primary immunodeficiency (5); Autoimmunity (4); cerebral infarction (4); Crohn disease (4); malaria (4); neutropenia (4); otitis media (4); adenocarcinoma (3); cardiac hypertrophy (3); chronic granulomatous disease (3); diabetic retinopathy (3); granulocytosis (3); histiocytic sarcoma (3); HIV-1 infection (3); influenza infection (3); pneumococcal infection (3); spondyloarthritis (3); acne (2); acute kidney injury (2); acute myocardial infarction (2); Airway obstruction (2); alcoholic hepatitis (2); autosomal recessive disease (2); B-cell chronic lymphocytic leukemia (2); cardiovascular diseases (2).
A further 140 diseases each share a sentence with ITGB2 in 2 papers or fewer.